ENSG00000269179 (novel protein)
Gene: Protein-coding gene on chromosome 19 (49,909,501 to 49,958,391, reverse strand). Ensembl gene ENSG00000269179.
Genetic constraint (gnomAD): Missense variants: 40 observed, 48.53 expected, observed/expected ratio (o/e) 0.82, 90% interval 0.64 to 1.07. Synonymous variants: 25 observed, 21.75 expected, observed/expected ratio (o/e) 1.15, 90% interval 0.84 to 1.6.